TLR4 (toll like receptor 4)
Diseases named in the same sentence as TLR4 in open-access papers (continued):
Sharing a sentence is not in itself a finding about the gene and the disease.
colitis (continued). "In conclusion, probiotic VSL#3 inhibits the expression of NF-κB and TNF-α in rats with colitis through TLR4-NF-κB signal pathway, so it is expected to be a first choice drug for the treatment of colitis." (PMID 31497551, 2019). "To further investigate the mechanism of MRS in colitis, we focused on the TLR4-MyD88 signaling pathway, which is responsible for the expression of inflammatory cytokines and chemokine." (PMID 31182999, 2019). "The findings a study of NF-κB and TLR4 in patients with colitis are consistent with this experiment, which supports point of views in this study." (PMID 31497551, 2019). "In 2,4,6-trinitrobenzene sulfonic acid (TNBS)-induced rats colitis, magnolol reduces the activity of colonic myeloperoxidase, the levels of proinflammatory cytokines, and the mRNA expression of toll-like receptor 4 (TLR4)." (PMID 31240205, 2019). "The present in vivo and in vitro studies showed that the activation of TLR4 signaling was up-regulated in the DSS-induced colitis and LPS-activated macrophages." (PMID 31207873, 2019). "Through the use of a competitive TLR4 antagonist (C34) and Polymyxin we were able to selectively differentiate between total TLR4-driven lymphatic alterations/consequences during DSS induced colitis, and those driven by LPS." (PMID 30972059, 2019). "We aimed to investigate the effect of probiotic VSL#3 on NF-κB and TNF-α in rats with colitis and the correlation with TLR4-NF-κB signal pathway." (PMID 31497551, 2019). "Our data reveals not only the TLR4-driven lymphatic alterations during DSS-induced colitis, but the gross-mechanisms which they act." (PMID 30972059, 2019). "Compared with the normal group, mRNA levels of TLR4 and NF-κB in colitis rats were significantly increased, which were markedly down-regulated by different dosages of CP." (PMID 30042683, 2018). "TLR4 involvement is supported by the downregulation of miR-146a in TLR4 KO mice with DSS colitis compared with WT mice." (PMID 30478292, 2018). "In mouse pups, the acidic trisaccharide 3’SL was shown to promote colitis by inducing inflammation in a TLR4 mediated manner." (PMID 29990329, 2018). "To study the influence of bacterial antigen stimulation on the expression of miR-146a and immune activation through TLR2 and TLR4 we set up an experiment in which DSS colitis was induced in TLR2 and TLR4 knock out mice." (PMID 30478292, 2018). "An attenuated trend of the expression of p65, pp65, and TLR4 in TNBS-induced colitis rats was also observed in the groups treated with CP." (PMID 30042683, 2018). "The flavonoid Baicalin improves colitis to a similar degree as mesalazine with a reduction in colonic TLR4 as measured by immunohistochemistry and a reduction in NF-κB-dependent pro-inflammatory cytokine production." (PMID 29515999, 2018). "In a murine model of DSS-induced colitis, an increase in mRNA and protein expression in intestinal epithelial cells for TLR4 that was correlated with IL-1β expression was demonstrated." (PMID 30138385, 2018). "Our study provided evidence for the first time that baicalein attenuated TNBS-induced colitis, at least in part, via inhibition of TLR4/MyD88 signaling cascade as well as inactivation of NLRP3 inflammasome." (PMID 29180692, 2017). "The effects of lactobacilli and bifidobacteria administration on TNF-α and TLR4 expression in a rat colitis model induced by TNBS were also investigated." (PMID 28555037, 2017). "Interestingly, in a mouse model of dextran sulfate sodium (DSS)-induced colitis, 1A6 could ameliorate inflammation and prevent the progression of the intestine inflammation; however, the blockade of TLR4 signaling by 1A6 could also cause a defect in the mucosal healing during the recovery stage." (PMID 28769820, 2017).
colitis (continued). "Deficiency of TLR4 and MyD88 have been shown to sensitize and mice to DSS mediated colitis and previous studies have concluded that TLR4 and MyD88 are required for the control of bacterial translocation and triggering the repair of the intestinal epithelium." (PMID 29259211, 2017). "To further confirm the relationship between LPS/TLR4 and TNFα/NOS2 induction, as well as the role of NF-κB signaling in ulcerative colitis and colitis associated tumorigenesis, we used ex vivo experiments." (PMID 28408791, 2017). "Tlr4 has been reported to regulate Cox2 expression in DSS-induced colitis, which is similar to our results in Hi Tannin Black DSS rats." (PMID 28346392, 2017). "TLR4 is known to play an important role in the development of colitis, and was shown to promote colon carcinogenesis in chronic colitis." (PMID 27105524, 2016). "Several studies have shown that TLR4 is implicated in DSS-induced mice ulcerative colitis and colitis-associated colorectal tumors." (PMID 27105524, 2016). "In this study, we sought to identify the upstream regulator of NLRP12 involvement in the development of DSS-induced colitis, and found that TLR4-mediated up-regulation of Blimp-1 led to the down-regulation of NLRP12 expression in DSS-induced colitis." (PMID 27105524, 2016). "In conclusion, we have identified the previously unrecognized regulatory axis of TLR4-Blimp-1-NLRP12 that modulates inflammatory response in dendritic cells during DSS-induced mice colitis." (PMID 27105524, 2016). "We also showed that C57BL/6 mice cohoused with villin-TLR4 mice develop more severe DSS colitis than singly housed C57BL/6 mice do." (PMID 26755160, 2016). "Taken together, the results suggest that the TLR4-Blimp-1 axis promotes DSS induced experimental colitis through the down-regulation of NLRP12." (PMID 27105524, 2016). "At the end of 4 weeks, acute colitis was induced in SH-WT, CH-WT, and villin-TLR4 (CH-VT) mice by the addition of 3% DSS to the drinking water for 6 days." (PMID 26755160, 2016). "The changes in the microbiota induced by increased epithelial TLR4 signaling are transmissible and exacerbate dextran sodium sulfate-induced colitis." (PMID 26755160, 2016). "We have previously shown that villin-TLR4 mice are more prone to DSS-induced colitis than their WT littermates." (PMID 26755160, 2016). "Our results further illustrated the critical role of TLR4 and Blimp-1 interaction in the development of colitis." (PMID 27105524, 2016). "In the context of infectious enteritis, TLR4 signaling facilitates pathogen colonization and dissemination and promotes infection-induced colitis." (PMID 26755160, 2016). "Here, we found an increased proportion of cells expressing CD11c and TLR-4 in MLN during colitis induction, which is consistent with the increasing amounts of Enterobacteriaceae and Akkermansia found on colonic mucosa." (PMID 24414342, 2015). "PF reduces dextran sodium sulphate (DSS)-induced colitis by suppressing the expression of toll-like receptor 4 (TLR4) and reducing the activation of nuclear factor-kappa B (NF-κB) and mitogen-activated protein kinase (MAPK) pathways." (PMID 26204936, 2015). "A few studies have also reported that curcumin can attenuate inflammation and subsequent inflammatory injury by inhibiting TLR4 expression in colitis, hepatic fibrosis and lung injury." (PMID 24669820, 2014). "In our animal models, we have found that mice constitutively expressing TLR4 have an increased severity of chemically-induced colitis and develop more colonic tumors." (PMID 24887394, 2014). "Expression of the S. Typhi Vi capsular polysaccharide in S. Typhimurium leads to an attenuation of these T3SS-1-independent inflammatory responses in the mouse colitis model, by reducing complement activation and TLR4 signaling." (PMID 24992093, 2014). "TLR2 and TLR4 up-regulation in epithelial cells in this TNBS-colitis model as well as the cytokine up-regulation indicate bacterial activation of mucosal defense and inflammation." (PMID 23382912, 2013).
colitis (continued). "Nevertheless, this is consistent with TLR4’s role in limiting bacterial translocation in a murine model of colitis." (PMID 24278135, 2013). "Results of these studies demonstrate that, in comparison with C57BL6 wild type mice, colitis severity was attenuated by TLR4 ablation, while the opposite was observed in TLR9−/− mice." (PMID 23372731, 2013). "Further, reports that demonstrate a protective role for TLR4 in models of colitis have typically been based upon the use of global TLR4 knockout mice, in which TLR4 signaling is disrupted in enterocytes as well as T-cells and myeloid cells." (PMID 23762089, 2013). "Analysis of mucosal damage score demonstrated that, with the exception of TLR4−/− mice which showed a less severe disease, the severity of the colitis was essentially similar in wild type, TLR2−/−, TLR9−/− and MyD88−/− mice (n = 6; p<0.05)." (PMID 23372731, 2013). "This is in contrast to decreased epithelial proliferation and significant epithelial injury recorded during DSS-induced colitis in Tlr4−/− mice." (PMID 24278135, 2013). "TLR4 and MyD88 KO mice both develop more severe colitis induced by DSS compared to wildtype (WT) controls, with increased bacterial translocation, shown by the greater positivity of mesenteric lymph node cultures for E. coli and Pseudomonas fluorescence." (PMID 24062746, 2013). "Blocking TLR4 at the beginning of DSS administration delayed the development of colitis with significantly lower DAI scores." (PMID 22665953, 2012). "Accordingly, it has been reported that Tlr4-deficient mice are less prone to colon carcinogenesis induced by azoxymethane in association with DSS, an experimental model which mimics colitis-associated carcinogenesis." (PMID 22242189, 2012). "Accordingly, systemic administration of a TLR4-blocking antibody impairs restoration of tissue integrity during DSS-colitis, despite limiting exaggeration of acute inflammatory responses induced by recruited cells." (PMID 22665953, 2012). "TLRs in non-immune cells have been implicated in multiple autoimmune and inflammatory diseases, including Hashimoto’s thyroiditis (TLR3 in thyrocytes), colitis (TLR4 in intestinal epithelial cells and type 1 diabetes (TLR3 in pancreatic ß-cells)." (PMID 22685570, 2012). "Adipose tissue TLR4 levels were higher in the Colitis + HFD group compared to controls and intermediate to the colitis and HFD groups." (PMID 22073943, 2011). "The expression of the leptin receptor b (Ob-Rb) and toll like receptor (TLR) 4 showed that the combination of diet and colitis was significantly related to TLR4 overexpression." (PMID 22073943, 2011). "We and others have shown that mucosal expression of EGFR ligands, AR and epiregulin, are regulated by TLR4 signaling during colitis." (PMID 24212947, 2011). "Recent findings in acute TNBS-induced colitis model in rats demonstrate that Curcumin-induced inhibition of intestinal inflammation involves TLR-4 and MyD88." (PMID 21151942, 2010). "Our results reveal for the first time that the induction of colitis or ileitis in mice is associated with marked increases in the luminal concentrations of PAMPs specific for TLR2, TLR4 and/or TLR5." (PMID 20161736, 2010). "We have also demonstrated in an animal model of acute colitis using dextran sulfate sodium that TLR4, through the adapter protein MyD88, is important in the intestinal response to epithelial injury and limiting bacterial translocation." (PMID 20976181, 2010). "The fact that macroscopic signs and inflammatory parameters of acute intestinal inflammation were reduced in TLR2-/-, TLR4-/-, and TLR2/4-/- mice prompted us to identify distinct gut bacterial populations associated with colitis severity." (PMID 17653282, 2007). "Induction of DSS colitis in TLR4-/- mice led to an altered neutrophil recruitment due to diminished MIP-2 expression by lamina propria macrophages." (PMID 16351713, 2005). "This indicates that DSS‐induced colitis activates the TLR4/MyD88/NF‐κB signaling cascade." (PMID 40994452, 2025).
colitis (continued). "Similarly, Gastrodin attenuates colitis and prevents tumorigenesis in mice by inhibiting TLR4/MD2/NF-κB signaling, offering potential as a therapeutic agent in colitis-associated cancer." (PMID 39976020, 2025). "The findings of the present study demonstrated that these genera exhibited significant correlations not only with conventional phenotypic indicators of colitis, but also with body inflammation, intestinal barrier function, and the LPS/TLR4/NF-κB/NLRP3 signaling pathway." (PMID 40130239, 2025). "CW supplementation inhibits the high levels of inflammation induced by DSS, suppressing excessive inflammatory mediators (serum TNF‐α, IL‐1β, and IL‐6), downregulating the overexpressed mRNA levels of TNF‐α, IL‐1β, IL‐6, TLR4, and iNOS, while upregulating IL‐10, thereby alleviating colitis." (PMID 39830908, 2025). "This demonstrates that 4-PBA can regulate TLR4/MyD88/NF-κB-mediated E. coli-induced colitis." (PMID 40076603, 2025). "Based on these findings, we hypothesize that inactivated AKK PROBIO may attenuate the initiation and progression of colitis by modulating the TLR4/NF-κB/NLRP3 signaling axis." (PMID 41376001, 2025). "A TLR4/NF‐κB/IRF4 signaling pathway is indispensable for M. elsdenii‐mediated DC activation and thereby leads to the augment of colonic Th1 and Th17 inflammation, resulting in an exacerbation of colitis‐associated tumorigenesis." (PMID 40801433, 2025). "Our study demonstrated that 4-PBA could relieve E. coli-induced colitis by improving gut microbiota structure and inhibiting the expression of pro-inflammatory cytokines through the TLR4/MyD88/NF-κB pathway." (PMID 40076603, 2025). "Toll-like receptor 4 (TLR4) functions as a sensor mediating the crosstalk between the intestinal commensal microbiome and host immunity; TLR4 deficiency enhances susceptibility to DSS-induced colitis." (PMID 41322271, 2025). "In this study, mice with DSS-induced colitis exhibited significant activation of the TLR4/MyD88/NF-κB pathway alongside the suppression of Nrf2 nuclear translocation and HO-1 expression, indicative of a self-perpetuating cycle of inflammation and oxidative stress that aggravates colonic injury." (PMID 40808691, 2025). "For example, polysaccharides from Dendrobium huoshanense have demonstrated significant anticancer potential, while those from Dendrobium officinale alleviate secondary pulmonary injury induced by colitis through the inhibition of TLR4 signaling and activation of the Nrf2 pathway." (PMID 41300540, 2025). "Furthermore, taurine deficiency has been shown to increase the susceptibility to DSS-induced colitis, while taurine pretreatment protected against experimental colitis in mice by enhancing intestinal barrier function and suppressing the TLR4/NF-κB pathway." (PMID 40242025, 2025). "Another study illustrated that baicalein could alleviate colitis symptoms by inhibiting the TLR4/MyD88 signaling cascade and activating the NLRP3 in mice." (PMID 39421730, 2024). "In a rat model of colitis, curcumin was shown to decrease disease activity, with reduced colonic mucosa damage, through the decreased expression of IL-27 via inhibition of the TLR4/NF-κB signalling pathway." (PMID 39123583, 2024). "Overall, this research shows that B. animalis may maintain intestinal barrier function, regulate inflammatory cytokines, prevent colitis caused by DSS in mice, block TLR4/MYD88/NF-κB activation, and modify the particular gut microbiota." (PMID 39323474, 2024). "Regarding quinic acid, one study 402 showed that this compound attenuated UC by inhibiting the TLR4-NF-κB and NF-κB-iNOS-NO signaling pathways, thereby reducing colitis-related complications such as oxidative stress, inflammation, apoptosis, and histopathological damage in the same animal models." (PMID 39494333, 2024).
colitis (continued). "In summary, we hypothesize that the administration of ruscogenin can attenuate DSS-induced colitis by improving intestinal barrier function, reducing the inflammation response and regulating pyroptosis via TLR4/NF-κB signaling pathway." (PMID 38790951, 2024). "Then, we used TAK‐242 into colitis mice by intraperitoneal injection, a selective inhibitor of TLR‐4, to observe whether targeted inhibition of peripheral inflammation could improve anxiety‐like behaviors in colitis mice." (PMID 38676295, 2024). "Furthermore, tissue-resident Vimentin+ mesenchymal stromal cells secrete PGE2 via the TLR4-Tpl2-COX2 pathway in the propagation phase of dextran sodium sulfate-induced colitis in mice and alleviate pathology of the large intestine." (PMID 39327633, 2024). "These exosomes activate TLR4 signal for promoting colitis progression and mucosal barrier injury." (PMID 38535999, 2024). "Colonic TLR4 expression is downregulated in CRF-deficient mice and is more susceptible to colitis." (PMID 39749341, 2024). "Furthermore, although we confirmed the finding that ruscogenin inhibits pyroptosis and thereby alleviates colitis through the TLR4/NF-κB pathway, transgenic mouse experiments are necessary to verify this pathway before using ruscogenin in IBD patients." (PMID 38790951, 2024). "Another study reported that orally given AuNPs (25 μg Au/kg) can prevent colitis by attenuating the inflammatory response mediated by Toll-like receptor 4 and oxidative stress but may lead to an imbalance of the intestinal flora of mice." (PMID 39199130, 2024). "Oral administration of MEVs in the colitis mouse model decreased intestinal inflammation by the inhibition of Toll-like receptor 4 (TLR4)- NF-κB and NOD-, LRR- and pyrin domain-containing protein 3 (NLRP3) pathways and restoration of the balance between T-reg and Th17 cells." (PMID 39519052, 2024). "Ultimately, our results suggest that AEEL could be used as a natural material with the potential to suppress colitis-induced systemic inflammation by regulating the JNK/TLR4 signaling pathway and could alleviate cognitive dysfunction in the brain." (PMID 38612870, 2024). "By applying TLR-4 mutant (lps−/lps-) mice, Chung and colleagues conducted the first investigation to examine the impact of probiotics on the progression of experimental colitis." (PMID 39323474, 2024). "The beneficial effects of rTs-gal on colitis may be achieved by controlling the intestinal flora and bacterial functions, which may reduce the generation of LPS and suppress the expression of TLR4, MyD88, and NF-κB." (PMID 38172977, 2024). "Evidence demonstrated that TLR4 is highly expressed in DSS-induced colitis mice." (PMID 38611304, 2024). "Via the pro-inflammatory Toll-like receptor 4 (TLR4) pathway, exposure to active ATIs can lead to intestinal inflammation and deterioration of pre-existing inflammatory diseases such as non-alcoholic fatty liver disease and colitis." (PMID 39064708, 2024). "There have been many reports suggesting that polysaccharides from natural plants are beneficial to intestinal health; for example, ginseng polysaccharides can improve TLR4/MyD88/NF-κB-induced colitis by inhibiting the activation of dextran sulfate sodium (DSS)." (PMID 37415978, 2023). "Antibiotic treatment also decreases intestinal LPS overload; in murine models of colitis-associated CRC, antibiotics and the TLR-4-blocking molecule Resatorvid are able to inhibit inflammation, decreasing TLR-4 signaling and TLR-4+ tumor-infiltrating macrophages." (PMID 36838231, 2023). "In this regard, TLR4 hyperactivation emerged as the major orchestrator for the development of the inflammatory reaction in colitis, compromising the regeneration of the intestinal mucosa and increasing over time the risk of developing inflammation-associated colon cancer." (PMID 37233492, 2023).